NPVF (neuropeptide VF precursor)
Description:
[Neuropeptide RFRP-1]: Efficiently inhibits forskolin-induced production of cAMP. Acts as a potent negative regulator of gonadotropin synthesis and secretion. Induces secretion of prolactin (By similarity). [Neuropeptide NPVF]: Efficiently inhibits forskolin-induced production of cAMP. Blocks morphine-induced analgesia. [Neuropeptide RFRP-2]: Shows no inhibitory activity of forskolin-induced production of cAMP.
Synonyms: C7orf9; RFRP
Tractability: Antibody: UniProt places it where antibodies can reach, with high confidence; UniProt predicts a signal peptide or a membrane-spanning region; its Gene Ontology location is reachable by antibodies, with medium confidence.
Gene: Protein-coding gene on chromosome 7 (25,224,570 to 25,228,486, reverse strand). Ensembl gene ENSG00000105954.
Subcellular location: Secreted
Gene Ontology:
Molecular function: neuropeptide activity; protein binding; signaling receptor binding
Biological process: negative regulation of gonadotropin secretion; neuropeptide signaling pathway
Cellular component: extracellular region
Genetic constraint (gnomAD): Loss-of-function variants: 13 observed, 11.51 expected, observed/expected ratio (o/e) 1.13, 90% interval 0.73 to 1.74. The upper end of that interval is the gene's LOEUF score, 1.74, which puts it in group 6 of 6, group 1 being the genes least tolerant of losing a copy. Missense variants: 186 observed, 170.28 expected, observed/expected ratio (o/e) 1.09, 90% interval 0.97 to 1.23. Synonymous variants: 46 observed, 58.23 expected, observed/expected ratio (o/e) 0.79, 90% interval 0.62 to 1.01.
Homologues: Orthologues: chimpanzee NPVF (98% identical), macaque NPVF (91% identical), dog NPVF (78% identical), rabbit NPVF (69% identical), pig NPVF (66% identical), guinea pig NPVF (65% identical), rat Npvf (59% identical), mouse Npvf (58% identical), tropical clawed frog npvf (32% identical), zebrafish npvf (20% identical).
Diseases named in the same sentence as NPVF in open-access papers:
NPVF is named in the same sentence as 2 diseases in open-access papers, as found by Europe PMC text mining. Sharing a sentence is not in itself a finding about the gene and the disease. The quoted sentences say what the papers report.
insomnia (1 paper, 2017). A sleep disorder characterized by difficulty in falling asleep and/or remaining asleep. "Finally, we observed that inhibition of NPVF signaling and ablation of NPVF neurons impair both the initiation and maintenance of sleep, hallmark characteristics of insomnia." (PMID 29106375, 2017).
NPVF also shares sentences with these, for which no sentence is quoted: Anxiety (1 paper).